SETD1A (SET domain containing 1A, histone lysine methyltransferase)
Diseases named in the same sentence as SETD1A in open-access papers (continued):
Sharing a sentence is not in itself a finding about the gene and the disease.
cognitive deficits (8 papers, 2021 to 2025). "Mice that carry a LoF mutation in SETD1A showed cognitive deficits, abnormal neuronal morphology, and transcriptional alterations, further implicating its role in SCZ etiology." (PMID 36424644, 2022). "It is interesting to speculate that deficits in Setd1a-mediated adult NSC maintenance and decreased adult hippocampal neurogenesis may occur later in life in SCZ patients with Setd1a mutations and contribute to their cognitive deficits." (PMID 38971831, 2024). "Reduced H3K4me2 methylation has been causally linked to the emergence of behavioral and cognitive deficits in other preclinical mouse models relevant to psychiatric and neurodevelopmental disorders, including models that are based on genetic deficiency of Shank3, Setd1a, and Kmt2c." (PMID 40102613, 2025). "To further assess the utility of SCZ-MoNNets as a quantitative phenotypic platform for drug discovery, we took advantage of recent findings indicating that LSD1 demethylase activity inhibitors, ORY-1001 and TCP, are effective in rescuing cognitive deficits when administered in adult Setd1a+/− mice." (PMID 35680927, 2022). "Setd1a+/– mice express impairments in social behavior as well as in working memory and learning which resemble some of the known deficits in human individuals with SETD1A haploinsufficiency, i.e., reductions in social skills, learning difficulties and cognitive impairments." (PMID 34803610, 2021).
developmental delay (8 papers, 2019 to 2025). "Another male patient presented with muscular hypotonia, developmental delay, and atypical autism, and carried a de novo heterozygous frameshift variant in SETD1A." (PMID 40558542, 2025). "Heterozygous pathogenic variants in SETD1A have been described in individuals with developmental delay, intellectual disability, subtle facial dysmorphisms, and behavioral and psychiatric problems (OMIM 619056)." (PMID 34345025, 2021). "SETD1A haploinsufficiency is known to cause a Mendelian disorder characterized by global developmental delay including delayed speech and/or language development, mild intellectual disability, subtle facial dysmorphisms, and behavioural and psychiatric symptoms (MIM: 619056)." (PMID 40225914, 2024). "More recently this conceptual linking has been extended by associating mutations in SETD1A with disorders that are clinically characterized as NDDs, symptomatically represented with developmental delay, intellectual disability, behavioral problems as well as early onset epilepsy." (PMID 34803610, 2021). "Moreover, the identical variant was independently reported to be pathogenic in a case of SETD1A haploinsufficiency disorder with broader and more severe symptoms including intellectual disability, global developmental delay, speech delay, and autism spectrum disorder." (PMID 40225914, 2024). "Germline pathogenic variants in two genes encoding the lysine-specific histone methyltransferase genes SETD1A and SETD2 are associated with neurodevelopmental disorders (NDDs) characterized by developmental delay and congenital anomalies." (PMID 37166351, 2023). "Our results indicate that the full clinical spectrum associated with SETD1A haploinsufficiency also includes speech delay in the absence of intellectual disability or global developmental delay." (PMID 40225914, 2024). "Interestingly, patients with SETD1A haploinsufficiency also present with global developmental delay and craniofacial dysmorphism, with a small percentage experiencing seizures in early childhood." (PMID 36581615, 2022). "Lack of symptoms indicating developmental delay or a psychiatric disorder suggests that proband 04, who carries the SETD1A frameshift, has a mild form of SETD1A-associated disorder." (PMID 29463886, 2019). "Of note, proband 01 does not have symptoms indicative of developmental delay or a psychiatric disorder and therefore presents with a mild phenotype compared to others with SETD1A haploinsufficiency." (PMID 40225914, 2024).
colon cancer (7 papers, 2014 to 2024). "When the YAP protein, a SETD1A non-histone substrate, is methylated by SETD1A, its migration out of the nucleus is inhibited and, consequently, YAP-TEAD transcriptional activity is increased, leading to colon cancer cell proliferation and tumor formation." (PMID 34201935, 2021).
epilepsy (7 papers, 2020 to 2024). A brain disorder characterized by episodes of abnormally increased neuronal discharge resulting in transient episodes of sensory or motor neurological dysfunction, or psychic dysfunction. "This case highlights novel clinical phenotypes and enhances our understanding of SETD1A-related epilepsy compared to previous reports." (PMID 39767570, 2024). "Reports on SETD1A-related epilepsy are limited, with clinical features observed in approximately 23% of cases." (PMID 39767570, 2024). "We also summarize the existing literature on SETD1A gene-related epilepsy to provide a reference for clinical diagnosis and treatment." (PMID 37928142, 2023). "Effective treatment strategies for SETD1A-related epilepsy remain unclear." (PMID 39767570, 2024). "Noticeable differences between both syndromes are the incidence of epilepsy, which is more common for SETD1B (20% in SETD1A, 78% in this cohort), and the absence of a male predominance for SETD1A (9 males of 19 cases)." (PMID 34345025, 2021).
Intellectual disability (7 papers, 2020 to 2025). "In humans, heterozygous mutations in the orthologous H3K4 methyltransferases (Trx = KMT2A/B, Trr = KMT2C/D, Set1 = SETD1A/B) cause neurodevelopmental disorders (NDDs), such as autism spectrum disorder and intellectual disability." (PMID 39869640, 2025). "Fourth, the candidate genes newly implicated in CAS were frequently associated with other neurodevelopmental disorders, such as epilepsy (e.g. GNAO1, GNB1, SETD1A) and/or intellectual disability (e.g. CDK13, CHD3, DDX3X, POGZ, SETBP1)." (PMID 36117209, 2023).
hepatocellular carcinoma (6 papers, 2021 to 2024). A malignant tumor that arises from hepatocytes. "In addition, the expression of SETD1A was obviously enhanced in hepatocellular carcinoma cell lines and tumor tissues and SETD1A knockdown enhanced sorafenib-induced proliferation inhibition and cellular apoptosis." (PMID 36475064, 2022).
acute myeloid leukemia (5 papers, 2014 to 2022). Acute myeloid leukemia (AML) is a group of neoplasms arising from precursor cells committed to the myeloid cell-line differentiation. "Histone methyltransferase SETD1A is critical for acute myeloid leukemia (AML) cell survival, but the molecular mechanism driving SETD1A gene regulation remains elusive." (PMID 36450243, 2022). "Aberrant expression of SETD1A results in the pathogenesis of human diseases, including acute myeloid leukemia (AML), colorectal cancer, and triple-negative breast cancer." (PMID 32629770, 2020). "In addition, a non-enzymatic function of SETD1A, a methyltransferase of H3K4, regulates the expression of genes involved in DNA damage response and is required for the survival of acute myeloid leukemia cells." (PMID 33257809, 2020).
ovarian carcinoma (4 papers, 2021 to 2025). A malignant neoplasm originating from the surface ovarian epithelium. "However, the function and underlying molecular mechanism of SETD1A in ovarian cancer (OV) remain markedly unknown." (PMID 36707804, 2023). "In summary, we show that SETD1A loss renders ATM-deficient and BRCA1-mutated breast, lung, and ovarian cancer cells resistant to PARPi by restoring HR, and that this is partly driven by defective EME1 transcription." (PMID 39994444, 2025). "We used cervical, breast, lung and ovarian cancer cells bearing mutations in BRCA1 or ATM and depleted SETD1A using siRNA or CRISPR/Cas9." (PMID 39994444, 2025). "While the expression of NOG, S1PR1, BTG4, and CREB5 genes was significantly increased, that of RASSF9, DNMT1, BST2, and SETD1A genes was significantly decreased in CFP1-deleted A2780 and ES-2 ovarian cancer cells, based on qRT-PCR results." (PMID 35864225, 2022).
periodontitis (3 papers, 2022 to 2024). An acute or chronic inflammatory process that affects the tissues that surround and support the teeth. "Quantitative evaluation using ImageJ2 (ver.2.15.0: National Institutes of Health (NIH), Bethesda, MD, USA) revealed that the expression of H3K4me3 and SETD1A in periodontitis rats was significantly increased by 2.0 times compared with control rats." (PMID 39456763, 2024). "Surprisingly, we have also observed high expression of MLL1 in NMOSD and periodontitis patients, but without explicit colocalisation within DNA, which may be related to MLL1 and SETD1A synthesis, but with limited capacity to colocalisation into cell nucleus." (PMID 38745328, 2024).
diabetes (2 papers, 2023 to 2024). "We discovered that diabetes causes histone modifications of H3K4me3 via the upregulation of SETD1A in gingival tissues." (PMID 39456763, 2024).
early-onset epilepsy (2 papers, 2021 to 2023). "Missense variants outside protein domains in SETD1A, and of unclear effect, have been associated with early-onset epilepsy with or without ID (MIM #618832), whereas LoF variants have been associated with a novel neurodevelopmental syndrome (MIM #611052)." (PMID 37152996, 2023).
invasive breast carcinoma (2 papers, 2019). A carcinoma that infiltrates the breast parenchyma. "We identified KMT2D, SETD1A and SETD2, included in the lysine methyltransferase activity function, as linked with poor prognosis in invasive breast cancer." (PMID 30990809, 2019). "Prevalence of mutations or translocations of SETD1A have not yet been reported cancer, however, SETD1A is amplified in mixed ductal and lobular and invasive breast carcinomas, suggesting that increased copy number might constitute one of the mechanisms responsible for its overexpression in cancer." (PMID 31253781, 2019).
Prostate Tumors (2 papers, 2015 to 2020). "The expression of SETD1A mRNA (GSE6099) was found to be higher in prostate tumors than that in normal prostate tissue." (PMID 32629770, 2020). "In addition, both SETD1A and FOXM1 were found to be overexpressed in mCRPC compared to their expression in primary prostate tumors (GSE35988, GSE32269)." (PMID 32629770, 2020).
speech disorder (2 papers, 2023 to 2024). A term referring to disorders characterized by the disruption of normal speech. "Remarkably, in recent studies, de novo pLoF variants in SETD1A have been identified twice in children ascertained based on their speech disorder, despite the relatively modest size of the cohorts being screened." (PMID 40225914, 2024).
acanthosis nigricans (1 paper, 2022). A melanotic cutaneous lesion that develops in the axilla and other body folds. "In addition to the cases mentioned in this paper, other rare disorders that have matched with therapeutic options include non-ketotic hyperglycinemia, MAPK8IP3-related disorder, EGFR-associated acanthosis nigricans, and SETD1A-related disorder." (PMID 36248623, 2022).
adenoma (1 paper, 2013). A neoplasm arising from the epithelium. "In some cases, these genes were uniquely up-regulated in residual tumors (e.g., Setd1a, Dyrk3), while in other cases the genes were up-regulated in both residual and untreated adenoma tumors (e.g., Suv39h1, Mll1)." (PMID 23520493, 2013).
Alzheimer disease (1 paper, 2024). A progressive, neurodegenerative disease characterized by loss of function and death of nerve cells in several areas of the brain leading to loss of cognitive function such as memory and language. "Interestingly, several transcriptome-wide significant and colocalized genes outside genome-wide significant GWAS loci point to biologically relevant pathways related to neurodevelopment and neurodegeneration (PICALM, a known Alzheimer disease gene, CAMSAP2, AGTPBP1, SETD1A, EPRS, PADI2 and PSAP)." (PMID 38811690, 2024).
Anxiety (1 paper, 2024). Intense feelings of nervousness, tension, or panic often arise in response to interpersonal stresses. "In terms of adult behaviour, we found evidence for an enhanced acoustic startle response in male Setd1a+/- mice and increased anxiety-related behaviour in both male and female Setd1a+/- mice." (PMID 39141687, 2024). "Exploration patterns in these tests demonstrated that both male and female Setd1a+/- mice showed avoidance of the more anxiety-inducing regions of each piece of apparatus, the central zone of the OFT and the open arms of the EPM." (PMID 39141687, 2024). "In terms of measures of anxiety, then our data from the open field (OFT) and elevated plus maze (EPM) assays are the first to demonstrate that Setd1a LoF can lead to a subtle anxiogenic phenotype." (PMID 39141687, 2024).
colorectal tumours (1 paper, 2017). "Thus, up-regulated SETD1A and its H3K4me3 product probably play a causal role in colorectal tumour cell growth by dysregulating the WNT signaling pathway." (PMID 28587163, 2017). "It is known that H3K4 methyltransferase SETD1A and H3K4me3 marks are generally up-regulated in human colorectal tumours." (PMID 28587163, 2017).
glioblastoma (1 paper, 2023). The most malignant astrocytic tumor (WHO grade IV). "Mass spectrometry analysis revealed the interaction partners of ASH2L in glioblastoma cell lines as SET1/MLL family members including SETD1A, SETD1B, MLL1 and MLL2." (PMID 37974198, 2023). "To address the essential role of ASH2L for glioblastoma cell survival further, we focused our attention to chromatin modifying complexes, specifically, SET1/MLL family of histone methyltransferases SET1 (SETD1A), SET1B (SETD1B), MLL1 (KMT2A), MLL2 (KMT2B), MLL3 (KMT2C) and MLL4 (KMT2D)." (PMID 37974198, 2023).
glioma (1 paper, 2023). A benign or malignant brain and spinal cord tumor that arises from glial cells (astrocytes, oligodendrocytes, ependymal cells). "Among the six methyltransferases for H3K4me3, SETD1A is associated with WHO malignancy in pediatric gliomas." (PMID 37444539, 2023). "WDR82 is relatively high in glioma vs. other cancers, which is the sole subunit in SETD1A-COMPASS, specifically associated with pediatric glioma WHO-grade malignancy and patient survival, regardless of histone mutation status." (PMID 37444539, 2023).
head and neck cancer (1 paper, 2022). A primary or metastatic malignant neoplasm affecting the head and neck. "According to the TCGA database, SETD1A is highly expressed in head and neck cancer, but the role of SETD1A in nasopharyngeal carcinoma is less studied, and the related mechanism is still unclear." (PMID 36475064, 2022).
infantile spasms (1 paper, 2023). A rare epilepsy syndrome characterized by onset of epileptic spasms in infants between 2 and 12 months of age, and rarely up to 24 months. "There have been no previous reports on the SETD1A gene causing infantile spasms." (PMID 37928142, 2023).
invasive ductal carcinoma (1 paper, 2022). "Additionally, the protein levels of SETD1A and SOX2 were significantly higher in invasive ductal carcinoma tissues than in the normal breast tissues." (PMID 35966598, 2022).
nasopharyngeal carcinoma (1 paper, 2022). A carcinoma arising from the nasopharyngeal epithelium. "Here, this study revealed the function of SETD1A in nasopharyngeal carcinoma that the expression of SETD1A was associated with nasopharyngeal carcinoma cells." (PMID 36475064, 2022). "The purpose of this research was to explore the specific biological function and the potential mechanism of SETD1A in nasopharyngeal carcinoma." (PMID 36475064, 2022). "Silence of SETD1A results in nasopharyngeal carcinoma cell proliferation inhibition and cell apoptosis." (PMID 36475064, 2022). "The assay of glucose uptake, lactate release, ATP level, western blot, cell proliferation, and cellular apoptosis analysis were performed to investigate the potential mechanism of SETD1A regulation in nasopharyngeal carcinoma." (PMID 36475064, 2022). "In conclusion, this study identified overexpressed SETD1A as a positive regulator of proliferation that induced nasopharyngeal carcinoma cells’ aerobic glycolysis via PI3K/AKT signaling activation in vitro." (PMID 36475064, 2022). "The SETD1A overexpression vector, si-NC, si-SETD1A#1, and si-SETD1A#2 were transfected into nasopharyngeal carcinoma cells to overexpress or knockdown SETD1A expression." (PMID 36475064, 2022). "Mechanistically, this study used si-NC, si-SETD1A#1, si-SETD1A#2, vector, or OE-SETD1A to knockdown or overexpress the SETD1A in nasopharyngeal carcinoma cells." (PMID 36475064, 2022). "This study was the first to show that SETD1A was upregulated in nasopharyngeal carcinoma cells and the overexpression of SETD1A significantly promoted the cell proliferation and glycolysis and suppressed the cellular apoptosis." (PMID 36475064, 2022). "By contrast, upregulated SETD1A significantly enhanced the cell proliferation and reduced the apoptosis ratio in nasopharyngeal carcinoma cells." (PMID 36475064, 2022). "In particular, the SETD1A may become a novel target for further inhibitor design to interfere with PI3K/AKT-dependent nasopharyngeal carcinoma progression." (PMID 36475064, 2022). "The assay of biofunction was used to explore the role of SETD1A in nasopharyngeal carcinoma cells." (PMID 36475064, 2022). "The SETD1A may become a novel biomarker for further inhibitor design to obstruct the PI3K/AKT-dependent nasopharyngeal carcinoma progression." (PMID 36475064, 2022). "Therefore, we conclude that SETD1A promoting the progression of nasopharyngeal carcinoma is mainly depended on the PI3K/AKT signaling activation." (PMID 36475064, 2022). "Moreover, SETD1A enhances aerobic glycolysis and cell biological function of nasopharyngeal carcinoma cells via PI3K/AKT signaling pathway." (PMID 36475064, 2022). "However, the role of SETD1A in nasopharyngeal carcinoma remains unclear." (PMID 36475064, 2022). "The results from cancer-TCGA database analysis identified that SETD1A was upregulated in nasopharyngeal carcinoma compared to normal tissue." (PMID 36475064, 2022). "However, in this study, the correlation between SETD1A, PI3K/Akt/FOXO3a pathway, and chemo-resistance in nasopharyngeal carcinoma has not been explored yet, which will be the direction of future studies." (PMID 36475064, 2022).
neuroblastoma (1 paper, 2022). Neuroblastoma (NB) is the most common solid, extracranial childhood tumor. "Disruption by Setd1a haploinsufficiency of mitochondrial and metabolic functions characterized by a downregulation of associated nuclear transcripts is consistent with previous studies in human neuroblastoma." (PMID 35531971, 2022). "Six hundred and seventeen downregulated genes observed in a human neuroblastoma cell line following knockdown of SETD1A were also significantly enriched for GO:0005739 Mitochondrion genes." (PMID 35531971, 2022).
Neurodevelopmental delay (1 paper, 2023). "Pathogenic variants in SETD1A have been reported in association with early onset epilepsy, neurodevelopmental delay and an increased risk of schizophrenia (MIM:618832; MIM:619056), and variants in SETD1B (MIM:619000), SETD2 and SETD5 (MIM:616761) have also been associated with NDDs." (PMID 37166351, 2023).
Parkinson (1 paper, 2025). "Rare-variant and pleiotropy analyses further implicate SETD1A and BC070367 in psoriasis–Parkinson’s comorbidity." (PMID 41465136, 2025).
Parkinson disease (1 paper, 2025). A progressive degenerative disorder of the central nervous system characterized by loss of dopamine producing neurons in the substantia nigra and the presence of Lewy bodies in the substantia nigra and locus coeruleus. "Complementary pleiotropy-informed analyses have identified additional loci, including SETD1A and BC070367, connecting psoriasis and Parkinson’s disease via immune–epigenetic interactions." (PMID 41465136, 2025).